TNC (tenascin C)
Diseases named in the same sentence as TNC in open-access papers (continued):
Sharing a sentence is not in itself a finding about the gene and the disease.
glioma (continued). "This study aimed to show that an extracellular protein called Tenascin-c (TNC) is involved in VM formation and that TNC knockdown inhibits VM in glioma." (PMID 31754182, 2019). "To investigate the relationship between IL-33 and TNC, we stimulated glioma cells with different concentrations of IL-33 for 6 h and then examined the expression levels of TNC by RT-PCR and Western blot analyses." (PMID 31889095, 2019). "Further, TNC knockout attenuates the invasiveness of glioma cells and inhibits glioma growth in vitro." (PMID 31889095, 2019). "This includes an overexpression of tenascin-C at the invasive front, increasing motility of glioma cells via interactions with β1 or αvβ3 integrins, probably via an activation of FAK and inhibition of RhoA." (PMID 31003495, 2019). "Here, we showed that downregulation of TNC strongly repressed IL-33-mediated glioma cell invasion but had little impact on migration." (PMID 31889095, 2019). "This study aimed to investigate the role of TNC in VM formation and the effect of TNC knockdown on VM in glioma." (PMID 31754182, 2019). "As expected, TNC-knockdown increased Annexin V positive cells in both U251 and A172 glioma cells (*p < 0.05, **p < 0.01)." (PMID 31754182, 2019). "Animal studies demonstrated that IL-33 significantly promoted glioma progression, and immunohistochemical staining showed that treatment with IL-33 significantly increased TNC expression." (PMID 31889095, 2019). "To better understand the mechanisms behind the altered diffusion parameters (D*, λ, K, and half-life), we compared the levels of glioma chondroitin sulfate proteoglycan, tenascin C, and collagen type IV in 10- and 20-day gliomas by immunohistochemistry." (PMID 28678913, 2017). "We found that glioma aggression and patient prognosis correlate with HIF1α levels and the stiffness of a tenascin C (TNC)-enriched ECM." (PMID 27820599, 2016). "We have previously shown that Notch signaling induces Tenascin C (TnC), a marker for tumor malignancy which stimulates glioma cell migration and invasion through the canonical Notch pathway." (PMID 23451269, 2013). "On the other hand, high levels of tenascin-C produced by glioma tumour tissues actively hindered T-cell migration, resulting in an accumulation of T cells in the peritumoral region." (PMID 23922799, 2013). "Its expression has been correlated with the degree of tumor neovascularization in human gliomas and melanoma cells, and tumor cells xenografted into TNC knockout mice demonstrate a regression of tumor growth and angiogenesis." (PMID 22481923, 2012). "Laminin is arguably the most important of all ECM proteins in the context of brain tumour invasion, while tenascin C is expressed in high quantities in human gliomas." (PMID 22363471, 2012). "The increased expression of TNC in glioma, breast, and colon cancers has been correlated with a poor survival prognosis." (PMID 22481923, 2012). "To date, the most promising siRNA therapeutic application in glioma is represented by an interference RNA targeting tenascin-C (TN-C)." (PMID 22685651, 2012). "Tenascin-C (TNC) was first discovered as a protein in the stroma of gliomas and as a myotendinous antigen in connective tissues." (PMID 22481923, 2012). "Additionally, Decorin (DCN), which plays a role in collagen fibril assembly, and Tenascin-C (TNC), commonly expressed in gliomas, were also downregulated." (PMID 40813676, 2025). "The ECM components form the cellular microenvironment and is often overexpressed in glioma cells; components such as hyaluronic acid, brevican, tenascin-C, fibronectin, thrombospondin, and specific integrins and receptors are known to promote cell adhesion and migration." (PMID 39874307, 2025). "Then, CCK-8, wound healing, invasion assays, and flow cytometry were conducted to investigate whether downregulation of TNC could alter glioma cell proliferation, migration, invasion ability, and inhibit the cell cycle." (PMID 39090080, 2024).
glioma (continued). "Subsequently, we performed MeDIP analysis with TDG knockdown and control U251 cells, as well as checked the alterations in TNC expression using RT-qPCR and protein blotting, indicating that TDG knockdown greatly enhanced the DNA methylation level of TNC, suppressing TNC expression in glioma cells." (PMID 39090080, 2024). "Besides angiogenesis, TNC also participates in vascular mimicry and transdifferentiation of glioma stem cells." (PMID 39090080, 2024). "Tenascin-C is a favorable substrate for glioma invasiveness; its effect is mediated through MMP-12." (PMID 36980765, 2023). "In addition, TNC is present in several stem cell niches, including neural stem cells (NSCs) and glioma stem cells (GSCs)." (PMID 36033448, 2022). "New studies have found that some biomarkers, such as ITGA-5 and Tenascin-C, could predict glioma prognosis, and are closely related to the immunosuppressive microenvironment, particularly for the clinical application of immunotherapy in glioma." (PMID 35812432, 2022). "Nevertheless, in gliomas, TNC is expressed by malignant tumor cells." (PMID 36033448, 2022). "In this study, by analyzing the data of the Cancer Genome Atlas (TCGA) and the Chinese Glioma Genome Atlas (CGGA), we found tenascin-C (TNC) was associated with the prognosis of LGG patients and could reflect the status of the tumor immune microenvironment." (PMID 35371015, 2022). "Furthermore, many reports have demonstrated that TNC expression is related to the infiltrative phenotype of many tumors, including gliomas." (PMID 36033448, 2022). "However, a fragment composed of all FNIII domains induced a reduction, whereas the integral TNC molecule led to an increase in glioma cell proliferation." (PMID 36033448, 2022). "To date, TNC has been found to play complex modulatory roles in glioma cell adhesion." (PMID 36033448, 2022). "Aside from the regulation of cell function, TNC is also involved in the regulation of the angiogenesis of glioma, as reported by a previous study, which revealed that TNC interacts with targets of Yes-associated protein (YAP) to modulate tumor angiogenesis in a bidirectional manner." (PMID 33876384, 2021). "In particular, a few findings indicate that TNC might be involved in glioma pathogenesis; however, these findings are far from conclusive." (PMID 33876384, 2021). "TNC is an extracellular matrix protein and was reported to induce VM in glioma and melanoma." (PMID 34588421, 2021). "Also, SMOC1 has even been identified as a new cancer-related protein by interacting with tenascin-c, and it inhibits the tenascin-c induced chemo-attractive effect in U87 glioma cells." (PMID 34869577, 2021). "Tenascin-C (TN-C) near blood vessels is more highly concentrated in glioblastomas than in low-grade astrocytic tumors and is expressed in human glioma in vivo." (PMID 34149360, 2021). "Assessment of the temporal progression of these tumors showed initial establishment of the tumor that was halted, or in some cases regressed, as evidenced by tumor remnants (i.e. glioma scar) detected by a glioma derived extracellular matrix protein known as tenascin-C." (PMID 33447733, 2020). "In addition, glioma malignancy grade, and poor prognosis correspond with a high expression of Tenascin-C." (PMID 32560557, 2020). "Additionally, Gal-3 is able to directly interact with Tenascin-C, and the two molecules have been involved in homotypic cancer cell adhesion in glioma." (PMID 33013832, 2020). "Furthermore, TNC knockdown significantly induced G2/M arrest and apoptotic cell death in glioma cells." (PMID 31754182, 2019). "Next, we determined endogenous TNC gene and protein expression levels in pediatric glioma cell lines, including three supratentorial high-grade glioma (HGG) cell lines (KNS42, SF9402, SF9427) and six DIPG cell lines (SF7761, SF8628, DIPGIV, DIPGXIII, DIPG14 and DIPG007)." (PMID 31092287, 2019).
glioma (continued). "Therefore, targeting TNC expression is a potentially useful method to inhibit VM formation in glioma and decrease anti-angiogenic therapeutic resistance." (PMID 31754182, 2019). "Furthermore, the TNC+ cell population highly overlapped with the ST2+ cell population in human glioma specimens." (PMID 31889095, 2019). "Taken together, this evidence inspires us to investigate the influence of the IL-33/ST2 signalling pathway on TNC expression in glioma cells and to explore whether this signalling pathway promotes tumour progression." (PMID 31889095, 2019). "Furthermore, TNC knockdown significantly suppressed VM formation and proliferation in glioma cells in vitro and in vivo, with a reduction in cellular invasiveness and migration." (PMID 31754182, 2019). "To ascertain whether TNC is essential for IL-33-induced glioma invasion and migration, we knocked down TNC in U251 cells using shRNA constructs." (PMID 31889095, 2019). "In contrast, TNC overexpression is found in a variety of disease states and multiple cancers, including adult and pediatric supratentorial high grade glioma (HGG) and pediatric ependymoma, as well as breast, non-small cell lung, colorectal, and pancreatic cancers." (PMID 31092287, 2019). "Therefore, in the present study we aimed to comprehensively characterize TNC expression patterns, clinicopathological correlates and biological effects in pediatric glioma, including DIPG." (PMID 31092287, 2019). "Our data suggest that interleukin-33 (IL-33) may promote the accumulation of TNC protein by autocrine or paracrine modes of action in glioma." (PMID 31889095, 2019). "Contactin-1, tenascin-C and tenascin-R have adhesion and migration effects in glioma cells." (PMID 25238264, 2014). "Furthermore, high tenascin-C expression correlates with a low survival prognosis in cancers such as glioma, breast, colon and lung carcinoma." (PMID 23145140, 2012). "Furthermore, glioma stem cells (GSCs) secrete tenascin-C (TNC) that together with the acidic environment, resulting from the incremented anaerobic glycolysis generated by tumor cells, promotes the migration of malignant cells and the increase in angiogenic factors." (PMID 41596575, 2026). "Indeed, tumor specimen studies revealed a close relation between the number of macrophages and the Tenascin-C content in the glioma extracellular matrix, suggesting that Tenascin-C may represent a permissive substrate for macrophagic migration in gliomas." (PMID 36980765, 2023). "Thus, TNC appears to facilitate regulation of glioma cell adhesion turnover." (PMID 36033448, 2022). "Furthermore, overexpression of various ECM components is observed in gliomas, including hyaluronic acid, brevican, tenascin-C, fibronectin and thrombospondin as well as specific integrins and other receptors interacting with ECM components, which lead to adhesion and migration of glioma cells." (PMID 36289737, 2022). "Although miR-107 expression is down-regulated in glioma tissues and cell lines, its overexpression can directly target and regulate Notch2, which inhibits the migratory and invasive capacity of glioma cells, a known target for Tenascin-C and COX-2 trans-activation." (PMID 36479040, 2022). "Thus, targeting the IL-33/NF-κB/TNC signalling pathway may be a useful therapeutic approach in glioma." (PMID 31889095, 2019). "Thus, we investigated the detailed role of TNC in glioma cells." (PMID 31754182, 2019). "However, the regulation of TNC expression in glioma has remained unclear until now." (PMID 31889095, 2019). "Similarly, knockdown of TNC inhibited the invasiveness of glioma cells." (PMID 31889095, 2019). "Consistent with NS-culture-derived glioma cells with high invasiveness, genes highly expressed in 51A were those encoding markers of neural stem/precursor cells (NANOG, POU3F2, POU5F1, and SALL2), and pro-invasive proteins (AGAP2, EPHA2, FOXM1, PDGFRA, and TNC)." (PMID 29113349, 2017).
glioma (continued). "Tenascin-C (TNC) promotes Akt phosphorylation, upregulating MMP-9 expression and facilitating vasculogenic mimicry and glioma invasion." (PMID 40284474, 2025). "Culturing glioma cells in a stiff ECM enhances HIF1A expression, which subsequently increases the expression of tenascin C, a critical component in the aggressiveness of gliomas." (PMID 40150879, 2025). "GCL_TI specifically upregulates RG markers TNC, HOPX, PTPRZ1, and VIM, astrocyte markers CLU, LGALS1, as well as genes involved in migration and glioma network formation such as CD44, SPARC, and GAP43 (One peak)." (PMID 36823172, 2023). "Glioma aggressiveness and patient outcomes have also been found to correlate with HIF-1α levels and tenascin C-enriched ECM stiffness." (PMID 36076905, 2022). "Glioma cells also secrete their own ECM components such as HA, brevican, tenascin-C, fibronectin, and thrombospondin, which enhance the mobility and invasiveness of glioma cells." (PMID 35448036, 2022). "Higher concentrations of collagen, fibronectin, laminin, hyaluronic acid, tenascin C, and vitronectin are present in the ECM of GBM and have been shown to have important roles in the onset and glioma progression." (PMID 36276147, 2022). "Tenascin-C is an ECM protein that induces filopodia formation, is overexpressed in gliomas, and is produced by the tumor cells." (PMID 35053605, 2022). "In the present study, TNC positively regulated PI3K/AKT signaling in glioma cells, and activation of PI3K/AKT signaling reversed the effect of TNC knockdown on cell functions, including proliferation and stemness, and chemosensitivity to paclitaxel." (PMID 33876384, 2021). "The present study aimed to detect the effect of tenascin C (TNC) on cell function and chemosensitivity to paclitaxel and phosphatidylinositol 3-kinase/protein kinase B (PI3K/AKT) signaling in glioma cells." (PMID 33876384, 2021). "Previously, we have shown the increased levels of stem cell genes, including SOX2, OCT4, and GLI1 in these glioma cell lines that coincide with the presence of the CD44 and TNC in all the exosome samples from CCM." (PMID 32708613, 2020). "Among them, TNC is the most significant glioma ECM component, and its expression level is closely related to the grade of glioma development." (PMID 32875951, 2020). "Here, we characterize TNC expression in patient derived pediatric supratentorial HGG (n = 3) and DIPG (n = 6) cell lines, as well as pediatric glioma tumor (n = 50) and normal brain tissue specimens (n = 3)." (PMID 31092287, 2019). "In the present study, the expression levels of TNC, IL-33, and ST2 were measured in glioma tissue specimens, and the impact of altered IL-33 expression on TNC was investigated in vitro and in vivo." (PMID 31889095, 2019). "Tenascin-C (TNC), a very large multimeric glycoprotein, is overexpressed in human glioblastomas, leading to a highly motile and invasive phenotype of glioma cells." (PMID 31889095, 2019). "Therefore, our data support the hypothesis that TNC is involved in VM formation in glioma cells." (PMID 31754182, 2019). "This study showed that chondroitin sulfate proteoglycan, tenascin C, and collagen IV were the three main ECS components of a typical glioma cell, and participate in the microenvironment of glioma cell growth to affect its progression and transfer behavior." (PMID 28678913, 2017). "Herolde-Mende and colleagues correlated glioma grade and patient survival with the amount of a key ECS component (tenascin C) in MGs." (PMID 25101239, 2014). "Integrated DNA and RNA analysis of low-grade and high-grade proneural gliomas identified increased expression and gene amplification of several genes including GLIS3, TGFB2, TNC, AURKA, and VEGFA in proneural GBMs, with corresponding loss of DLL3 and HEY2." (PMID 20838435, 2010). "These genes had varying degrees of glioma-specific splicing and included APPA4, CLTB, DYNC1I2, NF1, RTN4 and TNC." (PMID 18474104, 2008).
glioma (continued). "Excitingly, tenascin-C (TNC), a crucial ECM glycoprotein involved in the process of cell growth, cell-substrate junction and ECM-receptor interaction, was markedly downregulated in TDG knockdown glioma cells." (PMID 39090080, 2024). "Our research concentrates on the demethylation of TDG in gliomas, demonstrating that upregulation of TDG expression in glioma cells leads to a significant downregulation of TNC methylation levels, thereby promoting TNC expression." (PMID 39090080, 2024). "To verify that the downregulation of methylation levels of TNC in gliomas is mediated by active DNA demethylation of TDG, we confirmed by ChIP- qPCR assay that TDG was able to combine with the chr9: 117826025 position of TNC, participate in the DNA demethylation process of TNC." (PMID 39090080, 2024). "Interestingly, most of these proteins are ECM molecules and contribute to the invasiveness of glioma cells, including FN1, TNC, LAMC1, COL1A1, EGFR, CDK6, and COL6A2." (PMID 37059730, 2023). "The results have shown that miRNA clusters could promote the expression of TNC and COX-2 by activating Notch2, thereby increasing the angiogenesis and invasion of gliomas." (PMID 36421704, 2022). "TNC expressed on GBM cells decreased the T cell amoeba-like shape formation and paralyzed migration, while transmigration of T cells through the monolayer and ECM of glioma cell lines lacking TNC was obviously increased." (PMID 36033448, 2022). "Remarkably, although TNC can activate high levels of phosphorylated FAK in endothelial cells, leading to microvascular migration, it stimulates low levels of FAK phosphorylation in glioma cells." (PMID 36033448, 2022). "Tenascin-C synthesis is known to be up-regulated in glioma and T-cells accumulate on the border of tumor and normal brain in association with high TNC deposition." (PMID 36276147, 2022). "Moreover, TNC was also considered a target gene of the transcription factor SOX4, which is overexpressed in many human malignancies, including glioma." (PMID 36033448, 2022). "Differentially expressed genes (DEGs) in the glioma samples relative to normal samples were screened from the GEO database, and five prognostically relevant BM-related genes, including NELL2, UNC5A, TNC, CSPG4, and SMOC1, were selected using Cox regression analyses for the risk score model." (PMID 36292695, 2022). "In addition, several mechanisms that are involved in the regulation of TNC expression, such as IL-33/NF-κB/TNC and NOTCH/RBPJκ/TNC, were found to increase the motility of glioma cells." (PMID 36033448, 2022). "In addition, 5 hub genes in hub network 2 were related to the poor prognosis of gliomas, including F5, IGFBP5, TNC, SCG3, and IGFBP3." (PMID 35387222, 2022). "Tenascin-C (TNC) is an extracellular matrix glycoprotein almost undetectable in adult tissues but highly expressed in the TME, which correlates with poor patient survival in several malignancies, including glioma." (PMID 35056924, 2021). "In U87 glioma cells, SMOC1 inhibits the tenascin-c-induced chemo-attractive effect." (PMID 34869577, 2021). "In addition, glioma cells synthesize and deposit ECM proteins, such as tenascin-C (TN-C), laminin (LM), fibronectin (FN), and type IV collagen (C-IV), which facilitate the tumor cell motility." (PMID 33917452, 2021). "Additionally, glioma cells can secrete their own ECM components, including HA, brevikan, tenascin C and thrombospondin, as well as fibronectin, which are actively expressed in the ECM of the developing nervous system along cell migration paths." (PMID 33059753, 2020). "TNC overexpression is thought to contribute to tumorigenesis by facilitating extracellular matrix remodeling, cell migration and angiogenesis, and co-localizes with CD133 expression in glioma stem cells." (PMID 31092287, 2019). "Glioma cells in vitro and in situ express various ECM components that modulate their microenvironment and promote migration, including collagens, laminins, brevican, tenascin-C and SPARC." (PMID 19712474, 2009).